NR4A1 (nuclear receptor subfamily 4 group A member 1)
Diseases named in the same sentence as NR4A1 in open-access papers (continued):
Sharing a sentence is not in itself a finding about the gene and the disease.
cancer (continued). "It has been recognized in CRC tissues that aberrant NR4A1 expression in cancer tissues and cells of the TME acts to promote cell growth and survival by serving as an important mediator of the WNT/β-catenin and AP-1 signaling pathways." (PMID 33634114, 2021). "During cancer development, Nur77 (also called NR4A1, TR3, or NGFIB) acts as a unique nuclear receptor to regulate a variety of functions, including cell proliferation, apoptosis, and invasion." (PMID 33537093, 2021). "Several anticancer agents, such as cytosporone B and its analogs, are known to induce apoptosis via NR4A1-dependent pathways in cancer cells." (PMID 33923503, 2021). "Since NR4A1 has different functions depending on subcellular localization in various types of cancer model, we compared the distribution and subcellular localization of NR4A1 between MCF7 and TamR cells by nuclear and cytoplasmic fractionation." (PMID 34209871, 2021). "Many apoptosis-inducing agents induce cell death in cancer cells through the induction of the nuclear export of NR4A1, which can form a pro-apoptotic complex with bcl-2 to disrupt mitochondria and induce apoptosis." (PMID 34072371, 2021). "Particularly, AXN321 (aka DIM-C-pPhOH) acts as an NR4A1 antagonist that inhibits pro-oncogenic pathways in cancer cells." (PMID 34654459, 2021). "Oppositely, NR4A1 knockdown decreases cancer cellular rate and angiogenesis through activating the apoptotic pathways." (PMID 33328994, 2020). "NR4A1 regulates proliferation and apoptosis in cancer cells by transcriptionally regulating target genes." (PMID 33172112, 2020). "NR4A1 is found to be overexpressed in numerous cancers, leading to increased proliferation and survival in these cancer cells via upregulating some target genes, including cyclin D2, E2F1, and survivin." (PMID 33328994, 2020). "We observed that knockdown of NR4A1 dramatically increased isoharringtonine-induced cancer cell death in A549 tumorspheroids by activating the intrinsic apoptosis pathway." (PMID 33172112, 2020). "One mitochondria-mediated pathway is reported to be involved in the NR4A1-induced apoptosis of cancer cells." (PMID 31839811, 2019). "It has been reported that, the NR4A1 export-related apoptosis is regulated by its heterodimerization with retinoid X receptor alpha (RXRα) in numerous cancer cells." (PMID 31839811, 2019). "NR4A1 and NR4A2 are also two early responding genes associated with cancer and chronic inflammatory diseases, including that affecting the kidneys." (PMID 31392215, 2019). "Together, these data show that Nr4a1 is regulated by PTMs and that it is integral for apoptosis in cancer cells." (PMID 31683815, 2019). "Due to this, Nr4a1, Nr4a2 and Nr4a3 are potential therapeutic targets in many cancers, however their specific roles vary between tissues and among tumors from the same organ." (PMID 31683815, 2019). "Plenty of evidence suggests that NR4A1 is over-expressed in numerous cancer types, including pancreatic, bladder, colon, and cervical cancers as well as melanoma, where it exhibits the pro-oncogenetic activity and enhances cell survival and/or proliferation." (PMID 31839811, 2019). "We found in three different cancer cell lines that NR4A1 is substantially localized outside of the nucleus and does not appear to undergo major relocalization upon exposure of cells to DIM-Ph-4-CF3+ OMs–." (PMID 29861853, 2018). "In summary, our findings are consistent with a first framework of the mechanism-of-action of DIM-Ph-4-Xs as anti-cancer agents: The compounds interact with the LBD of NR4A1." (PMID 29861853, 2018). "In summary, these results indicate that DIM-Ph-4-CF3+OMs– induces apoptosis of cancer cells through specific binding to NR4A1." (PMID 29861853, 2018). "In summary, for cancer cells, NR4A1 acts as a survival factor in the nucleus, but transforms into a killer after migrating to mitochondria." (PMID 29498706, 2018).
cancer (continued). "Some of the earliest studies of NR4A1 in cancer cells demonstrated the novel pathway in which the caged retinoid compound CD437, several analogs, and diverse apoptosis-inducing agents caused apoptosis in cancer cell lines by inducing nuclear export of NR4A1." (PMID 29498706, 2018). "Independently of DIM-Ph-4-CF3+ OMs–, the bulk of NR4A1 localized to the cytoplasm in various cancer cell lines, suggesting a cytoplasmic mechanism-of-action of DIM-Ph-4-CF3+ OMs– in UPR induction and cell death." (PMID 29861853, 2018). "For cancer cells, NR4A1 acts as a survival factor in the nucleus, but it transforms into a killer when immigrated to mitochondria." (PMID 30013988, 2018). "Here, we describe this unreported compound, its analogs, their impact on cancer cell viability and apoptosis, and NR4A1 as a plausible target in their apoptosis induction pathway." (PMID 29861853, 2018). "Taken together, this study provides a novel mechanism of Creb3l1 activation by Nr4a1 that adds important understanding to transcriptional mechanisms not only in the hypothalamus but also possibly more broadly within cancer research." (PMID 29311806, 2017). "The orphan nuclear receptor NR4A1 (nuclear receptor subfamily 4 group A member 1) is overexpressed in various tumors and cancer cell lines." (PMID 29207620, 2017). "In our previous studies, BP was examined for antihepatocellular carcinoma activity by inducing Nur77 (also known as NR4A1) expression, which led to caspase-3-dependent apoptosis and triggered an antiplatelet effect through PDGF reduction." (PMID 27199755, 2016). "Like NDRG1, Nur77 (also called TR3 or NR4A1) is a hypoxia-inducible protein that plays either pro-malignant or anti-malignant roles depending on the cancer cell type and cellular environment." (PMID 26359353, 2015). "It has been shown that NR4A1 maintains low levels of stress in cancer cells by regulating expression of TXNDC5 and IDH1 that in turn maintain high levels of cellular reducing agents." (PMID 26035713, 2015). "The function of NR4A1 in cancer cells has also been extensively investigated and in solid tumors, there is evidence that this receptor exhibits unique functions that are dependent on its subcellular location." (PMID 26035713, 2015). "On one hand, NR4A1 induces cell death; on the other hand, NR4A1 silencing induces apoptosis in several cancer lines." (PMID 23071566, 2012). "Other studies in cancer cell lines showed that several NR4A1-regulated integrins, including β1-, β4-, α5- and α6-integrins, were coregulated by NR4A1 interactions with Sp1, Sp3 and Sp4; however, the role of individual Sp TFs was gene and cell context-dependent." (PMID 39858066, 2025). "These conflicting roles of NR4A1 that NR4A1 may play different roles depending on the type and location of the cancer." (PMID 40666103, 2025). "While targeting NR4A1 may be beneficial in certain cancers, increasing NR4A1 levels can also prove to be beneficial in other instances." (PMID 40508074, 2025). "Therefore, detailed functional analysis of NR4A1 expression, transcriptional activity, and localization and the development of drugs that alter NR4A1 function will be useful in developing treatments for diseases such as cancer." (PMID 40746844, 2025). "This regulation is through suppressing the transcription and activity of SREBP1 target genes, such as FASN and SCD1, which suggests that NR4A1 agonists may potentially be useful in managing SREBP1-driven cancers." (PMID 40427160, 2025). "Because NR4A1 is involved in diseases such as cancer, NR4A1 may be an important pharmacological target." (PMID 40746844, 2025). "This work highlights the importance of understanding NR4A1’s role in cancer and suggests that targeting it could help to manage BC progression in the future." (PMID 40164686, 2025).
cancer (continued). "In addition, the role of NR4A1 in cancer depends on the degree of expression and the subcellular site and is characterized by tissue selectivity." (PMID 40666103, 2025). "Notably, MP7 was associated with stress meta program (MP5) in pan‐cancer studies, sharing 14 common genes, including ATF3, EGR1, FOSB, GADD45B and NR4A1." (PMID 40292733, 2025). "Thus, NR4A1 has pleiotropic regulatory effects on cancers, which are dependent on the expression of specific genes that are under the transcriptional control of NR4A1 in different contexts." (PMID 40164686, 2025). "To address the functional role of the NR4A1-downstream RE, we screened the TCGA cancer database." (PMID 38791553, 2024). "As such, we believe that NR4A1 is a valid target for cancer immunotherapy." (PMID 38334978, 2024). "To test the hypothesis that a cancer-type-specific MALAT1/NR4A1 axis modulates the expression of NR4A1, we evaluated the effect of this axis in specific cancer cell types." (PMID 38791553, 2024). "Notably, Cytosporone B, a natural agonist for NR4a1, has been explored for its therapeutic potential in cancer and fibrosis-related diseases." (PMID 38834564, 2024). "Though the cancer cell-intrinsic roles of NR4A1 have been extensively characterized in previous studies, our current study strongly supports that NR4A1 degradation leads to immune activation within the TME." (PMID 38334978, 2024). "Therefore, to understand the role of this axis in cancer, we correlated the chromatin accessibility of an NR4A1-downstream RE and the expression of the NR4A1 gene in TCGA data." (PMID 38791553, 2024). "NR4A1 overexpression may attenuate malignant progression in some tumors and may also serve as a drug target for cancer chemotherapy." (PMID 37833290, 2023). "Emerging evidence also suggested that translocation of Nr4a1 into the mitochondria of cancer cells induces their apoptosis, whereas nuclear Nr4a1 in these same cells may actually promote survival." (PMID 37161357, 2023). "Additionally, quercetin exhibits anti-cancer activity by binding the NR4A1 protein and inhibiting NR4A1-dependent transactivation in cells." (PMID 37569275, 2023). "We found that NR4A1 was correlated with AKT pathway in cancer." (PMID 36566195, 2022). "Previous studies have shown that the pro-oncogenic activity of NR4A1 in cancer cells also involves the regulation of some Sp1-mediated expression of antiapoptotic genes, such as survivin and bcl-2, and maintenance of appropriate intracellular levels of reactive oxygen species (ROS)." (PMID 35563670, 2022). "Cancer metabolism provides innovative opportunities for next-generation anticancer therapies that could be further improved using novel NR4A1 agonists or antagonists that simultaneously regulate NR4A1 and its downstream signaling pathways." (PMID 36052242, 2022). "NR4A1 is thought to participate in fatty acid uptake and oxidation to affect cancer cell fate." (PMID 36052242, 2022). "In TMM-free cancer cells, NR4A1 prevents cell death via a JNK/parkin-dependent mitophagy." (PMID 36359738, 2022). "In addition, the paradoxical roles of NR4A1 in regulating glucose metabolism in cancer were investigated." (PMID 36052242, 2022). "Recent reports shown that NR4A1 exhibits unique metabolic regulating effects in cancers." (PMID 36052242, 2022). "Nonetheless, the two side effects of NR4A1 have been observed on glucose metabolism, underscoring the complex and cell depend on its metabolic regulation, demonstrating NR4A1 acts as a potential therapeutic target in malignant tumors." (PMID 36052242, 2022). "However, when NR4A1 was reintroduced into the cells, the aggressive cancer progression promoted by overexpressed YTHDF2 was substantially hindered." (PMID 36566195, 2022). "Studies have discovered several nuclear NR4A1-dependent pro-apoptotic pathways in cancer cells." (PMID 33923503, 2021).
cancer (continued). "In addition, the nuclear receptor Nur77, encoded by the NR4A1 gene, is commonly upregulated in MB and leads to a proliferative state that promotes cancer progression, and it was also reported to be another target of miR-124." (PMID 34552822, 2021). "Studies in this laboratory initially identified 1,1-bis(3′-indolyl)-1-(p-hydroxyphenyl)methane (CDIM8) and the 4-carboxymethyl phenyl analog as NR4A1 ligands that act as antagonists and inhibit NR4A1-dependent pro-oncogenic pathways and genes in breast and other cancer cell lines." (PMID 34072371, 2021). "NR4A1 is an early response gene promptly induced by various cellular stimuli and plays an important role in various physiological processes and diseases, including cancer." (PMID 34209871, 2021). "NR4A1 has been found to be involved in promoting cancer invasion and metastasis." (PMID 33072067, 2020). "These opposing effects of NR4A1 depend on the type and stage of cancer." (PMID 33172112, 2020). "The role of NR4A1 protein in cancer is also currently unclear." (PMID 32664456, 2020). "Furthermore, NR4A1 knockdown extensively induces apoptosis in tumorspheroids that display low sensitivity to isoharringtonine-induced cancer cell death." (PMID 33172112, 2020). "Abnormal NR4A1 expression has been detected in multiple human cancer types." (PMID 31839811, 2019). "These controversial reports regarding NR4A1 in cancer highlights the possibility that the complex role of NR4A1 in cancer may be specific to the types or subtypes of cancers." (PMID 28903348, 2017). "Our data now supports the investigation of both Nr4a1 and Creb3l1 in cancer studies." (PMID 29311806, 2017). "The identification of Nr4a1 as a transcription factor of the Creb3l1 gene may have importance in cancer research." (PMID 29311806, 2017). "Previous studies show that NR4A1 acts as a coactivator of genes with GC-rich promoters (pathway 3) that play a role in cancer cell proliferation and survival, and these include survivin, bcl-2, cyclin D1, epidermal growth factor receptor (EGFR) and the oncogene cMyc." (PMID 27144436, 2016). "In contrast, our studies show that C-DIMs act through nuclear NR4A1 in cancer cells." (PMID 26035713, 2015). "The orphan nuclear receptor NR4A1 exhibits pro-oncogenic activity in cancer cell lines." (PMID 26035713, 2015). "It is possible that the opposing effects of NR4A1 expression in different cancers may be explained by differences in post-translational modifications of NR4A1 and thereby its subcellular localization." (PMID 25269081, 2014). "The specific function of NR4A1 as a transcriptional regulator in cancer remains unclear." (PMID 40164686, 2025). "The NR4A1‐IEG axis may be therefore lost in aggressive cancer." (PMID 39980141, 2025). "In addition, the DiNiro networks also uncovered several molecular interactions in mouse CD8+ T cells: (i) identifying the regulatory factor of HAVCR2, the NR4A1 gene (also called Nur77), which is a known critical mediator of T cell dysfunction and exhaustion in chronic inflammation and cancer." (PMID 36879901, 2023). "Current targeting of NR4A1 is still at pre-clinical stages, but the genetic evidence has strongly established NR4A1 as a good target for immune therapeutics to eliminate Tregs and/or rejuvenate Texh cells, as well as targeting the invasive and metabolic pathways in cancer cells." (PMID 39872303, 2023). "All these genes (AP2M1, FKBP11, GALNT6, BDNF, COL9A3 and NR4A1) favor relevant features of cancer progression, indicating that their epigenetic activation in CTCs of CRC patients under treatment could be a key event for the development of therapy resistance and cancer progression." (PMID 38188020, 2023). "Therefore, for one thing, further studies could focus on the diverse functions of NR4A1 on cancer immunity by glycolysis reprogramming." (PMID 36052242, 2022).
cancer (continued). "Our previous studies showed that the antiapoptotic activity of NR4A1 was due in part to the regulation of pro-survival genes with GC-rich promoters such as survivin (mechanism 1) and maintenance of intracellular oxidative stress at low levels in cancer cells (mechanism 2)." (PMID 35563670, 2022). "Furthermore, the inhibition of NR4A1 decreases cell growth and induces apoptosis in many cancer cells in vitro and in vivo, and NR4A1 inhibitors or antagonists are being characterized as a new class of antitumor agents for the treatment of solid tumors overexpressing this receptor." (PMID 35563670, 2022). "Additionally, NR4A1 also participated in cancer immunity by regulating metabolic pathways." (PMID 36052242, 2022). "Interestingly, the overall reported role of NR4A1 in cancer is paradoxical in the literature." (PMID 28903348, 2017). "Additionally, several studies reported that HLA-DRA could affect tumors and NR4A1 has been correlated with various carcinomas." (PMID 26367387, 2015). "However, induction of NR4A1 also occurs in response to apoptosis inducing factors in cancer cells." (PMID 24528603, 2014). "Interestingly, NR4A1 has contrasting roles in cancer as well." (PMID 23071566, 2012). "Mechanically, NR4A1 bound with the 3′UTR and gene body of IEGs, generating accessible chromatin domains that were detected in about half of breast and other cancers." (PMID 40002690, 2025). "Considering NR4A1 can play a biphasic role depending on the cancer type and TME composition, it will be critical to carefully assess such characteristics to classify patients and predict the therapeutic benefit of NR4A1 modulation." (PMID 40508074, 2025). "Nur77 (NR4A1) and HNF4α (Hepatocyte Nuclear Factor 4 Alpha) further contribute to BCa biology by regulating gene expression in cancer cells." (PMID 40806474, 2025). "The potent antitumorigenic activity of the DIM-3,5 analogs are due to several factors including their activity as dual NR4A1/NR4A2 inverse agonists that inhibit the pro-oncogenic pathway/genes, such as PD-L1, regulated by both receptors in cancer cells." (PMID 40313760, 2025). "Although there were some binding-assay-specific differences in their KD values and KD(NR4A1)/KD(NR4A2) ratios, each of the DIM-3,5 and DIM8-3,5 analogs bound both receptors and are dual receptor ligands that act as inverse agonists in cancer cell lines." (PMID 38540704, 2024). "A functional crosstalk between another member of NR4A subfamily NR4A1 (Nur77, NGFI-B) and β-catenin in EMT mediation has been shown in other cancers." (PMID 38531859, 2024). "In pancreatic cancer, NR4A1 (Nur77, TR3) regulates TXNDC5 expression, maintains low levels of stress by ROS in cancer cells, and promotes pancreatic cancer cell proliferation." (PMID 38629066, 2024). "In solid tumors, NR4A1 and NR4A2 are negative prognostic factors, they exhibit pro-oncogenic activities, and these can be inhibited by bis-indole derived compounds (CDIMs) which bind NR4A1 and NR4A2 and act as antagonists in cancer cells." (PMID 37175855, 2023). "On the contrary, negative LASSO coefficients were found for the genes ADRB2, CRYAB, NR4A1, CMTM5, ZBTB16, SYNE3, and RAD51, which were downregulated in cancer compared with normal samples." (PMID 36552262, 2022). "Nuclear receptor subfamily 4 group A member 1 (NR4A1) is an orphan nuclear receptor known to regulate proliferation and apoptosis of cancer cells." (PMID 33172112, 2020). "We detect spatial proximity of areas consisting of apparent cancer glands (“FOSB-enriched”), inflammation (“AQP3-enriched”) and reactive stroma (“NR4A1-enriched”)." (PMID 29925878, 2018). "These authors demonstrated inhibition of cancer cell proliferation and function as NR ligands with DIM-Ph-CF3 being an NR4A1 and PPARγ agonist, and DIM-Ph-4-OMe a selective NR4A1 agonist." (PMID 29861853, 2018).